ANP32B (acidic nuclear phosphoprotein 32 family member B)
Diseases named in the same sentence as ANP32B in open-access papers (continued):
Sharing a sentence is not in itself a finding about the gene and the disease.
infection (6 papers, 2014 to 2025). The state of being infected such as from the introduction of a foreign agent such as serum, vaccine, antigenic substance or organism. "Instead, the mouse variant of ANP32B that has serine and aspartic acid at these sites is likely the dominant form which supports infection." (PMID 31179971, 2019). "In Vero cells, ANP32B expression was suppressed during infection, but this profile was reversed upon milk supplementation." (PMID 41157297, 2025). "In general, H3N2 and H5N1 infection induced IFN-α, TNF-α, MCP-1 (CCL-2), IL-1β, and IL-6 responses in ANP32B+/+ mice were reduced in ANP32B−/− mice, particularly 3 days post infection." (PMID 32231671, 2020). "Reconstitution of dKO cells with both ANP32A and ANP32B proteins by transient transfection prior to infection restored PR8 virus replication." (PMID 31217244, 2019). "Taken together, these results imply that both ANP32A and ANP32B support infection in humans, but only ANP32A performs this role in chickens, with ANP32B being unable to help the polymerase." (PMID 31179971, 2019). "In contrast, infection with bovine-derived H5N1 upregulated ANP32B in MDCK and MDBK cells." (PMID 41157297, 2025). "Virulent MTB appears to consistently engage in host epigenetic orchestration, over the entire duration of infection, to evade host immune defences through ANP32B throughout the extended infection duration and ARP2/3 proteins during the latter half of the infection cycle." (PMID 38138142, 2023). "However, infection of ANP32B−/− mice with H3N2 or H5N1 IAV revealed significantly reduced virus loads, inflammatory cytokine response and reduced pathogenicity compared to ANP32B+/+ mice." (PMID 32231671, 2020). "Therefore, we determined the lung transcriptome of H3N2 or H5N1 IAV infected ANP32B+/+ and ANP32B−/− mice at 3 days post infection." (PMID 32231671, 2020). "After 20 h of infection, nuclear accumulation of NiV M was only detectable in mCherry-ANP32B expressing cells (arrows), whereas no nuclear accumulation was observed in cells devoid of mCherry-ANP32B (arrowheads)." (PMID 24823948, 2014). "In A549 cells, infection with both bovine- and mink-derived H5N1 induced marked downregulation of ANP32B." (PMID 41157297, 2025). "Nipah virus infection of the shRNA knock-down cells at an MOI of 0.01 and virus titration at 20, 24 and 45 hrs post infection revealed, that the ANP32B knock-down in shRNA 765 and 767 cells did not affect virus release." (PMID 24823948, 2014).
cancer (5 papers, 2016 to 2024). A tumor composed of atypical neoplastic, often pleomorphic cells that invade other tissues. "In addition, phosphorylation of AKT, an upstream regulator of cell cycle-associated proteins, is lower coincident with reduced ANP32B upon silencing and in both mouse and human cancers." (PMID 26844697, 2016). "Among the 7 model genes, 4 genes were differentially expressed in HCC cells and normal para-cancer tissues, namely, ANP32B, FTCD, ADH4 and PON1." (PMID 35413690, 2022). "ANP32B knockdown also significantly inhibits in vitro and in vivo growth of cancer cells by inducing G1 arrest." (PMID 26844697, 2016). "Dysregulation of ANP32B has been shown to participate in the development of human cancers." (PMID 38192816, 2024). "NCOA5 and ANP32B were reported previously in various cancer types." (PMID 30779739, 2019). "Members of the acidic leucine-rich nucleophosphoprotein 32 (ANP32) family, which mainly includes ANP32A, ANP32B, and ANP32E, are abnormally expressed and have prognostic value in certain cancers." (PMID 35280441, 2022).
tumor (4 papers, 2016 to 2024). "In the physiological context, knockout of ANP32B impedes the proper mammalian development, whereas in the pathological context, ANP32B deficiency functions as a suppressor of tumor growth and transformation." (PMID 26844697, 2016). "And the tumor luminous flux histogram indicated a significant decrease in the ANP32B knockdown group compared to the control group." (PMID 38383388, 2024). "The patients presenting tumor low ANP32B exhibited significantly advanced pathological stage relative to patients presenting tumor high ANP32B." (PMID 28486557, 2017). "This study demonstrates that a low tumor/non-tumor ratio of ANP32B mRNA expression is related to advanced UICC stage." (PMID 28486557, 2017). "Lower paired photos show images of specimens from a patient who presented lower expression of ANP32B in HCC tissue than in non-tumor tissue." (PMID 28486557, 2017). "Increased ANP32B in tumors and knockdown models also correlated with high p-AKT expression, indicating a possible mechanism through which ANP32B exerts its effect on cell proliferation and tumor progression." (PMID 26844697, 2016). "In vivo experiments further demonstrated that ANP32B knockdown effectively inhibited tumor growth." (PMID 38383388, 2024). "Furthermore, the fluorescence imaging outcomes of liver, spleen, and bone samples of mice indicated a substantial reduction in tumor burden within the ANP32B knockdown group when compared to the control group." (PMID 38383388, 2024). "Furthermore, the knockdown of ANP32B in AML cells exhibited a remarkable inhibition of tumor growth in vivo." (PMID 38383388, 2024). "ANP32B plays a significant role in promoting tumor proliferation in AML." (PMID 38383388, 2024). "Furthermore, the H&E staining analysis demonstrated a notable reduction in tumor cells within liver, spleen, and bone marrow samples from the ANP32B knockdown group in comparison to controls." (PMID 38383388, 2024). "Among the 31 patients, 16 belonged to the tumor low ANP32B group." (PMID 28486557, 2017). "Consistent with the in vitro findings, reduction of ANP32B led to a significant inhibition of tumor size at the fourth week after injection, which could be partially reversed by re-expression of ANP32B." (PMID 26844697, 2016). "Thus, we determined the mRNA expression index of T and NT specimens from each patient, calculated the T/NT ratio, and divided the patients into two groups: one with higher ANP32B expression (tumor high ANP32B) and another with lower ANP32B expression (tumor low ANP32B) in T than in NT." (PMID 28486557, 2017). "Furthermore, ANP32B knockdown tumor cells showed obviously weaker Ki-67 staining compared with control tumor cells, which could be also reversed by re-expression of ANP32B, suggesting that ANP32B knockdown indeed decreased cell proliferation in vivo." (PMID 26844697, 2016). "Middle paired photos show images of specimens from a patient who presented similar expression of ANP32B in HCC and non-tumor tissue." (PMID 28486557, 2017). "Upper paired photos titled “Tumor high ANP32B” show images of specimens from a patient who presented higher expression of ANP32B in HCC tissue than in non-tumor tissue." (PMID 28486557, 2017). "In tissues from patients with HCC, a low tumor/non-tumor ratio of ANP32B mRNA expression was related to advanced UICC stage (p = 0.032)." (PMID 28486557, 2017). "Downregulation of ANP32B in HCC may result in decreased sensitivity to apoptosis, thereby contributing to tumor progression." (PMID 28486557, 2017). "Finally, the results of the study on human tissues are expressed as the ratio of ANP32B expression between tumor and non-tumor tissues." (PMID 28486557, 2017).
ANP32B also shares sentences with these, for which no sentence is quoted: acute leukemia (1 paper); autoimmune encephalitis (1); B-cell acute lymphoblastic leukemia (1); experimental autoimmune encephalomyelitis (1); follicular lymphoma (1); gastric cancer (1); immune deficiencies (1); ischemic stroke (1); neurologic diseases (1); rectal tumor (1); Sepsis (1).